CYP3A5 (cytochrome P450 family 3 subfamily A member 5)
Diseases named in the same sentence as CYP3A5 in open-access papers (continued):
Sharing a sentence is not in itself a finding about the gene and the disease.
mucositis (1 paper, 2023). Mucositis is inflammation and damage of the mucous membranes lining the mouth and other parts of the gastrointestinal (GI) tract. "In this study, CYP3A5 non-expressors and patients with the 3R3R genotype (rs3832526, ASNS) showed a higher risk of developing mucositis and a higher number of mucositis events than those who express CYP3A5 and carry the 2R allele, respectively." (PMID 38044950, 2023). "Likewise, the mucositis classification tree shows both CYP3A5 and rs3832526 as the only variables that explain the presence of this toxicity." (PMID 38044950, 2023). "Patients who do not express CYP3A5, as well as those with the 3R/3R genotype (rs3832526, ASNS), had a higher risk of developing mucositis (OR = 4.55 [1.01–20.15], p = 0.049 and OR = 6.88 [1.88–25.14], p = 0.004)." (PMID 38044950, 2023). "Mucositis was significantly associated with ASNS (rs3832526; 3R/3R vs. 2R carriers; OR: = 6.88 [1.88–25.14], p = 0.004) and CYP3A5 (non-expressors vs. expressors; OR: 4.55 [1.01–20.15], p = 0.049) genes." (PMID 38044950, 2023). "Moreover, the CYP3A5 non-expressors or the 3R/3R patients present a higher number of mucositis events (p = 0.034 and 0.001, respectively)." (PMID 38044950, 2023).
myocardial infarction (1 paper, 2022). Gross necrosis of the myocardium, as a result of interruption of the blood supply to the area, as in coronary thrombosis. "Our study aims to assess the effects of the CYP3A4*22 allele and CYP3A5 expressor status in ticagrelor treated patients with a myocardial infarction, with respect to clinical endpoints and the most common side-effect dyspnea." (PMID 36545312, 2022). "Our study assessed the effects of the CYP3A4*22 allele and CYP3A5 expressor status in ticagrelor treated patients with a myocardial infarction, with respect to clinical endpoints and the side-effect dyspnea." (PMID 36545312, 2022).
non-small cell lung carcinoma (1 paper, 2020). A group of at least three distinct histological types of lung cancer, including non-small cell squamous cell carcinoma, adenocarcinoma, and large cell carcinoma. "Another study in Chinese population showed that CYP3A5 gene is closely related to the prognosis of patients with non-small cell lung cancer undergoing chemotherapy and surgical treatment." (PMID 32350633, 2020).
Optic neuropathy (1 paper, 2025). "CYP3A5 polymorphisms for drug dosing and visual evoked potentials for optic neuropathy can be used as early subclinical markers." (PMID 41246619, 2025).
osteoporosis (1 paper, 2018). A condition of reduced bone mass, with decreased cortical thickness and a decrease in the number and size of the trabeculae of cancellous bone (but normal chemical composition), resulting in increased fracture incidence. "We confirmed the causal role of adrenal‐secreted sulfated steroids in osteoporosis and identified two novel genetic loci (CYP3A5 and SULT2A1) to be important in the regulation of metabolites causing osteoporosis." (PMID 29232479, 2018).
parasitemia (1 paper, 2016). "CYP2C9 and CYP3A5 genes showed a trend for gametocytemia and parasitemia clearance rates." (PMID 27767381, 2016). "No main effect was observed for CYP3A5, but an interaction between gene over time on parasitemia elimination rate during treatment was disclosed (p = 0.007)." (PMID 27767381, 2016).
partial epilepsy (1 paper, 2013). "The research conducted does not support the significant prognosticating value of the studied polymorphisms of genes MDR1 and CYP3A5*3 in prognostication of pharmacoresistance of partial epilepsy in children." (PMID 23984379, 2013).
prostate adenocarcinoma (1 paper, 2025). "In a study of prostate adenocarcinoma (PRAD), the expression of CYP2A6, CYP3A5, and CYP4B1 genes was evaluated in prostate tissue using real-time quantitative PCR (RT-qPCR)." (PMID 40723371, 2025).
prostate tumor (1 paper, 2021). "Expression of P450 CYPs is tissue specific and CYP3A5 is the major isoform expressed in both normal and prostate tumor." (PMID 34570813, 2021). "The other major extrahepatic P450 isoform expressed in normal and prostate tumor is CYP1A1, bergamottin is a competitive inhibitor of CYP1A1 and can aid in cancer chemoprevension due to CYP1A1s role in carcinogenesis, this inhbitory effect is independent of bergamottins affect on CYP3A5 and AR." (PMID 34570813, 2021).
renal cell carcinoma (1 paper, 2023). "More surprising is the fact that some renal cell carcinomas express CYP3A5 at a level much higher than those found in normal tissues other than the liver." (PMID 37240915, 2023).
retrograde amnesia (1 paper, 2019). "In contrast, there was no direct correlation between genetic polymorphism of MDR1 or CYP3A5 and adverse reactions such as paradoxical response and retrograde amnesia." (PMID 31690757, 2019).
Skin rash (1 paper, 2020). A red eruption of the skin. "The polymorphisms of CYP1A2 plays an important role in the severity of skin rash, and the development of diarrhea was associated with SNPs in ABCB1 and CYP3A5." (PMID 32457635, 2020). "Correlation between CYP1A2 polymorphisms and severity of skin rash was observed, together with the correlation between the development of diarrhea and SNPs in ABCB1 and CYP3A5." (PMID 32457635, 2020). "The polymorphism of CYP1A2 was significantly associated with the severity of skin rash, and the development of diarrhea was associated with SNPs in ABCB1 and CYP3A5." (PMID 32457635, 2020).
toxic epidermal necrolysis (1 paper, 2021). Toxic epidermal necrolysis (TEN) is an acute and severe skin disease with clinical and histological features characterized by the destruction and detachment of the skin epithelium and mucous membranes. "CYP2C19*2 (681G>A, rs4244285) and CYP2C19*3 (636G>A, rs4986893) variants were associated with predisposition to Stevens-Johnson syndrome and toxic epidermal necrolysis (SJS/TEN) after CBZ administration and the absence of CYP3A5*3 (rs776746) might be a protective factor." (PMID 33804537, 2021).
tuberous sclerosis complex (1 paper, 2021). "For example, CYP3A4 and CYP3A5 polymorphism did not significantly affect sirolimus clearance rates in children with tuberous sclerosis complex." (PMID 34819851, 2021).
venous thromboembolism (1 paper, 2021). Occlusion of the lumen of a vein by a thrombus that has migrated from a distal site via the blood stream. "The study of SNVs of the CYP3A5 gene was conducted among 200 postmenopausal women who had an episode of venous thromboembolism and more than 500 comparable control groups." (PMID 33922084, 2021).
vitamin D insufficiency (1 paper, 2021). "Human migration from equatorial regions that increased vitamin D insufficiency, and an increasingly high salt diet, may have reduced the fitness of the sodium sparing CYP3A5*1 genotype in some populations." (PMID 33633318, 2021).
Wilson disease (1 paper, 2021). A very rare inherited multisystemic disease presenting non-specific neurological, hepatic, psychiatric or osseo-muscular manifestations due to excessive copper deposition in the body. "Gene expression of analyzed enzymes ranged between 18 and 65% compared to control group and significantly lower protein content of CYP1A1, CYP1A2, CYP2C8, CYP2C9, CYP3A4 and CYP3A5 enzymes was observed in Wilson’s disease." (PMID 34117631, 2021).
tumor (34 papers, 1999 to 2025). "In our current study, CYP3A5 expression was frequently up-regulated in tumor tissues and was associated with PDAC metabolism." (PMID 38560501, 2024). "In LIHC, we showed the association of high CYP3A5 expression with favourable OS, which is consistent with the reported tumour suppressive activity of this enzyme." (PMID 33202946, 2020). "Moreover, CYP3A5 has been suggested to serve as a tumor suppressor since lower CYP3A5 levels were associated with a more aggressive disease characterized by vascular invasion, poor differentiation, and shorter RFS and OS in HCC patients." (PMID 39682707, 2024). "Treatment with CYP3A5 inhibitor alone or together with TMZ effectively suppresses tumor growth in vivo." (PMID 39754188, 2025). "Hematoxylin and eosin (H&E) staining of tumors revealed that tumor sizes were smaller in mice implanted with CYP3A5 KO GSCs." (PMID 39754188, 2025). "We found that CYP3A5 KO in GSCs impeded xenograft tumor growth, as evidenced by bioluminescence imaging analyses." (PMID 39754188, 2025). "CYP3A4 and CYP3A5 transcripts and protein levels were higher in tumour tissue as compared with controls, but they were rather intermittent between patients." (PMID 38473371, 2024). "The combination of the CYP3A5*3/*3 and SRD5A2 A49T GG genotypes was associated with tumor clinical stages T2–T4, whereas the CYP3A5*3/*3 and KLK3 I179T CC/TC genotypes had increased OS in patients with metastatic PCa." (PMID 39682707, 2024). "Accordingly, CYP3A5 regulates the translocation of AR into the nucleus and downstream signaling, which leads to tumor." (PMID 36359206, 2022). "Measurement of mRNA levels of CYP3A genes in prostate samples has shown that basolateral cells of the prostate normally express CYP3A enzymes abundantly, but in the tumor tissue, mRNA and protein levels of CYP3A5 are markedly lower." (PMID 36359206, 2022). "A positive correlation with increasing tumour grade has been observed with the expression of CYP4V2, CYP4X1 and CYP4Z1; while CYP1B1, CYP3A5 and CYP51 were significantly associated with the ER status of the tumour." (PMID 33809117, 2021). "For example, some known oncogenes, such as KMT2B and TERT, were dominantly observed in tumor while fusion transcripts with CYP3A5, SERPING1, and WDR72 were only found in normal tissue." (PMID 29212479, 2017). "When comparing the relative mRNA concentration of CYP1B1, CYP2E1, CYP3A4, and CYP3A5 we detected in general higher regulation in tumor than their corresponding normal adjacent samples." (PMID 24699256, 2014). "In the present study, we compared the pattern expression of CYP1A1, CYP1A2, CYP1B1, CYP2E1, CYP2W1, CYP3A4 and CYP3A5 in paired tumor and normal tissue of child patients with RMS." (PMID 24699256, 2014). "Using real time quantitative RT-PCR, the gene expression pattern of CYP1A1, CYP1A2, CYP1B1, CYP2E1, CYP2W1, CYP3A4, and CYP3A5 were analyzed in tumor and adjacent non-tumor tissues from 13 child RMS patients." (PMID 24699256, 2014). "CYP3A4 in tumor and non-tumor samples have Ct mean<35, while CYP3A5 showed Ct means of 35.6 in normal tissue and 33.4 in tumor samples." (PMID 24699256, 2014). "In addition, we reported a novel way of CYP3A5 in mediating tumor chemoresistance, which is mediated by modulating NAD+/NADH levels to impact PARP1 DNA repair activity." (PMID 39754188, 2025). "However, only the drug metabolism by cytochrome P450 pathway was significantly enriched (fold enrichment = 13.4, FDR = 0.007) and all the five genes that fall within this pathway (FMO3, FMO2, FMO4, MAOB, CYP3A5) are upregulated in NS tumor tissue." (PMID 38978078, 2024). "Furthermore, there was a statistically significant correlation between CYP3A5 expression and tumor response to irinotecan therapy, suggesting a tumor-autonomous resistance to the treatment through increased CYP3A5-mediated metabolism." (PMID 37108395, 2023).
tumor (continued). "For instance, CYP3A5 expression is often low in tumor tissues at the level of transcripts and proteins in hepatocellular hepatoma; in particular, this underexpression contributes to worse overall survival of patients and to tumor metastasis." (PMID 36359206, 2022). "The overexpression of CYP2W1, CYP3A4 and CYP3A5 in tumor tissues suggests that they may be involved in RMS chemoresistance; furthermore, they may be exploited for the localized activation of anticancer prodrugs." (PMID 24699256, 2014). "Thus, the aim of the present study was to determine the mRNA expression pattern of seven representative CYPs (e.g., CYP1A1, CYP1A2, CYP1B1, CYP2E1, CYP2W1, CYP3A4, and CYP3A5) in paired tumor and normal tissue of childhood patients with RMS." (PMID 24699256, 2014). "In conclusion, among other factors, the altered protein levels of certain CYPs (e.g. CYP2C8, CYP3A4 and CYP3A5) in colon mucosa might contribute to the development of neoplasia in the colon." (PMID 16281975, 2005). "By performing a differential analysis between the two tumor cell compartments, we found that numerous genes associated with antigen presentation (e.g., HLA-DRA, CD74) were intensively upregulated in APHC, while a variety of metabolic enzymes (e.g., CYP3A5, ALDOB) were highly expressed in ANHC." (PMID 37336873, 2023). "Different expression patterns in tumor cells may be due to polymorphic expression of CYP3A5." (PMID 32316460, 2020). "Together, this study suggests that GSCs activate STAT3 to upregulate CYP3A5 to fine-tune NAD+/NADH for the enhancement of mitochondrial functions and DNA damage repair, thereby fueling tumor stemness and conferring TMZ resistance, respectively." (PMID 39754188, 2025). "For now, it is important to incorporate what is currently known about CYP3A4, CYP3A5, CYP2C8, and ABCB1 into the assessment of a patient when the mTOR pathway is a desired target in treating a tumor." (PMID 37240915, 2023). "The GEP analysis showed that the down-regulated genes in tumor tissue were CYP3A4 in 56 patients (61%), CYP2C8 in 44 patients (48%), CYP2C19 in 30 patients (33%), CYP2D6 in 11 patients (12%), CYP3A5 in 7 patients (8%) and CYP1B1 in 2 patients (2%)." (PMID 29774122, 2018). "The genes found to be down-regulated in tumor tissue were CYP3A4 in 56 patients (61%), CYP2C8 in 44 patients (48%), CYP2C19 in 30 patients (33%), CYP2D6 in 11 patients (12%), CYP3A5 in 7 patients (8%) and CYP1B1 in 2 patients (2%)." (PMID 29774122, 2018). "RT-PCR showed that both CYP3A5 mRNA and CYP3A7 mRNA were consistently present in both tumour and normal samples, while CYP3A4 mRNA was present in 65% of tumours and 90% of normal samples." (PMID 10206301, 1999). "In addition, CYP3A5 KO led to a significant reduction in the number of SOX2 + and Ki67 + tumor cells within GBM xenografts." (PMID 39754188, 2025). "Similarly, another publication that included young patients claimed that the CYP3A4 enzyme was present in most soft tissue Ewing sarcoma patients (81%), while CYP3A5 and CYP3A7 tumour expressions were fainter, in that order." (PMID 38473371, 2024). "For the castration-induced regression nadir group (i.e., those with the weakest or most unsuccessful castration-induced tumor regression), GSE1, CYP3A5, CTNNB1, CYP3A4, POU5F1, ABCB1, alkaline phosphatase liver/bone/kidney isozyme (ALPL), PROM1/CD133, ABCG2, and SOX2 were concomitantly upregulated." (PMID 34439112, 2021). "While studies investigating CYP3A protein expression in tumor samples have mainly found relatively high expression of both CYP3A4 and CYP3A5 both in tumor and non-tumor tissue." (PMID 31309254, 2019). "Specifically CYP1B1 and CYP3A5 genes were significant upregulated in one tumor tissue (patients 4, and 7, respectively), while upregulation of CYP2E1 and CYP3A5 mRNAs were significant in 4 (patients 4, 5, 6 and 13), and 2 (patients 5 and 12) paired tumor samples, respectively." (PMID 24699256, 2014).
tumor (continued). "In the current study, we focused on the previously unknown physiologic functions of CYP3A5 in tumor progression rather than on its drug metabolism-related effects." (PMID 38560501, 2024). "In addition, although not significant, a tendency of higher levels of CYP3A4 and CYP3A5 were found in the tumor tissue compared to the non-tumor tissue (mean: 1.02 versus 0.70, and 0.70 versus 0.43, respectively)." (PMID 24699256, 2014). "The use of a CYP3A5-specific antibody allowed us to exclude the expression of CYP3A5 in the tested tumours, but the involvement of CYP3A7 could not be further clarified because of the absence of a specific anti-CYP3A7 antibody." (PMID 14970873, 2004).
cancer (26 papers, 2007 to 2025). A tumor composed of atypical neoplastic, often pleomorphic cells that invade other tissues. "A higher MDZ elimination for white cancer patients and healthy Asian subjects having at least one wild-type CYP3A5*1 allele compared to CYP3A5*3/*3 patients have been reported." (PMID 17386084, 2007). "In addition, regarding CML, the response to the targeted cancer drug imatinib is associated with the CYP3A5*3 genotypes." (PMID 39523378, 2024). "Emerging evidence also suggests that the rs776746-G/A variant in intron 3 of the CYP3A5 gene may affect the individual’s risk of cancer development." (PMID 31137904, 2019). "At CYP3A5, strong signatures of positive selection were detected, though not connected to any dietary variable, but instead to an environmental factor associated with the Tropic of Cancer." (PMID 26018448, 2015). "Cytochrome P450 3A5 (CYP3A5) gene belongs to the cytochrome P450 superfamily, primarily involved in important processes such as drug metabolism, cancer biology, and organ transplantation." (PMID 40353060, 2025). "Considering that CYP3A5 takes part in lipid metabolism, it is worth investigating the relationship between CYP3A5 and lipid metabolism in cancer progression in the future." (PMID 38560501, 2024). "To investigate the role of CYP3A5 in cancer progression, we checked the level of CYP3A5 expression in different cancer cell lines based on the Cancer Cell Line Encyclopedia." (PMID 38560501, 2024). "Recent investigation into the aberrant expression of CYP3A5 in cancer, depending on the malignancy and ability to metastasize, uncovered a role of CYP3A5 in cancer progression, metastasis, and invasion." (PMID 36359206, 2022). "Additionally, our investigation revealed the preferential expression of CYP3A5 in cancer cells expressing the GSC markers SOX2 and CD133 via co-immunofluorescence (co-IF) staining of human GBM surgical specimens." (PMID 39754188, 2025). "However, this current study’s findings in participants with cancer suggest CYP3A5 genotype has a minimal role." (PMID 39184092, 2024). "Notably, CES2 and CYP3A5 serve as pivotal regulators in drug metabolic pathways across various cancer types." (PMID 38540686, 2024). "Since bergamottin is a natural CYP3A5 inhibitor, combining it with other cancer drugs may provide an opportunity to increase efficacy of treatment,especially in AAs expressing high levels of CYP3A5." (PMID 34570813, 2021). "The CYP3A5 genotype was studied in 78 Kenyan children with different cancer diagnoses." (PMID 31214762, 2019). "Moreover, principal component analysis of single-cell RNA-sequencing data of 65,655 GSCs and 14,207 GBM cells revealed that the area where CYP3A5 was highly expressed harbored cells that also markedly expressed cancer stem cell markers, such as PROM1, SOX2, EZH2 and NOTCH1." (PMID 39754188, 2025). "However, the role of CYP3A5 in cancer progression is context-dependent." (PMID 39754188, 2025). "Additionally, aberrant expression of CYP3A5 might promote cancer progression by altering the metabolism of cancer treatment drugs or endogenous molecules." (PMID 40353060, 2025). "However, this does not explain why CYP3A5 is highly expressed in some tumors even before drug treatment, and the role of CYP3A5 in cancer progression remains largely unknown." (PMID 38560501, 2024). "Simulated vincristine plasma concentration–time profiles in extensive and poor CYP3A5 metabolizers appeared to be reasonably well predicted by the developed PBPK model compared with observed vincristine concentrations in a population of cancer patients with unknown CYP3A5 genotype." (PMID 34080039, 2021). "However, it remains unclear whether CYP3A5 directly influences cancer progression." (PMID 38560501, 2024). "CYP3A5 is a cytochrome P450 (CYP) enzyme that metabolizes drugs and contributes to drug resistance in cancer." (PMID 38560501, 2024).